S1PR3 (sphingosine-1-phosphate receptor 3)
Diseases named in the same sentence as S1PR3 in open-access papers (continued):
Sharing a sentence is not in itself a finding about the gene and the disease.
immune diseases (1 paper, 2022). "C19orf12 + S1PR3 is most associated with these immune cells and S1PR3 can be used as a diagnostic marker of this kind of immune diseases." (PMID 35509008, 2022). "S1PR3 is most related to these immune cells and can be used as a diagnostic marker of such immune diseases." (PMID 35509008, 2022).
S1PR3 also shares sentences with these, for which no sentence is quoted: Bradycardia (7 papers); colon cancer (4); macular edema (4); cholestasis (3); acute respiratory distress syndrome (2); cardiovascular diseases (2); Glucose intolerance (2); metabolic disorder (2); triple-negative breast carcinoma (2); acute lung injury (1); acute lymphoblastic leukemia (1); airway hyperresponsiveness (1); anaplastic thyroid cancer (1); anemia (1); Arrhythmia (1); Arthritis (1); atrioventricular block (1); bacterial pneumonia (1); brain cancer (1); brain diseases (1); breast tumor (1); cancerous meningitis (1); ciliopathy (1); colorectal cancer (1); cytomegalovirus infection (1); dental pulp disease (1); Disseminated intravascular coagulation (1); endometriosis (1); ependymoma (1); Erythema (1).
A further 29 diseases each share a sentence with S1PR3 in 1 paper.